MBOAT4 (membrane bound ghrelin O-acyltransferase MBOAT4)
Description:
Catalyzes ghrelin acylation at 'Ser-3' using preferentially octanoyl-CoA, hexanoyl-CoA and decanoyl-CoA as acyl-CoA donors leading to ghrelin activity. In vitro also uses acyl-CoA donors of different lengths from short-chain (C2) to long-chain fatty acids (C16) knowing that acyl-CoA donors from butanoyl-CoA (C4) to dodecanoyl-CoA (C12) are more efficient compared to longer acyl-CoA donors, such as myristoyl-CoA (C14) and palmitoyl-CoA (C16) that are not efficient.
Synonyms: GOAT; OACT4; FKSG89
Tractability: Small molecule: a high-quality ligand is known. Antibody: UniProt predicts a signal peptide or a membrane-spanning region. PROTAC: a small molecule that binds it is known.
Target class: Enzyme; Transferase
Gene: Protein-coding gene on chromosome 8 (30,131,671 to 30,144,665, reverse strand). Ensembl gene ENSG00000177669.
Subcellular location: Endoplasmic reticulum membrane
Subcellular location (Human Protein Atlas): Golgi apparatus
Pathways (Reactome):
Metabolism of proteins: Synthesis, secretion, and deacylation of Ghrelin
Gene Ontology:
Molecular function: acyltransferase activity, transferring groups other than amino-acyl groups; serine O-acyltransferase activity
Biological process: peptidyl-serine octanoylation; lipid modification; peptide hormone processing
Cellular component: Golgi apparatus; endoplasmic reticulum; endoplasmic reticulum membrane
Genetic constraint (gnomAD): Loss-of-function variants: 7 observed, 6.81 expected, observed/expected ratio (o/e) 1.03, 90% interval 0.58 to 1.77. That is too few expected variants to judge how well the gene tolerates losing a copy. Missense variants: 431 observed, 487 expected, observed/expected ratio (o/e) 0.89, 90% interval 0.82 to 0.96. Synonymous variants: 181 observed, 201.2 expected, observed/expected ratio (o/e) 0.9, 90% interval 0.8 to 1.02.
Homologues: Orthologues: chimpanzee MBOAT4 (99% identical), macaque MBOAT4 (87% identical), rabbit MBOAT4 (80% identical), mouse Mboat4 (79% identical), rat Mboat4 (78% identical), pig MBOAT4 (78% identical), dog MBOAT4 (75% identical), guinea pig MBOAT4 (58% identical), tropical clawed frog mboat4 (44% identical), zebrafish mboat4 (35% identical). Paralogues in human: MBOAT1 (25% identical), MBOAT2 (23% identical), LPCAT3 (17% identical), MBOAT7 (17% identical), PORCN (16% identical).
Diseases named in the same sentence as MBOAT4 in open-access papers:
MBOAT4 is named in the same sentence as 31 diseases in open-access papers, as found by Europe PMC text mining. Sharing a sentence is not in itself a finding about the gene and the disease. The quoted sentences say what the papers report.
prostate carcinoma (7 papers, 2013 to 2025). A carcinoma that arises from epithelial cells of the prostate gland. "This is the first study to demonstrate the expression of GOAT/MBOAT4 mRNA in prostate cancer tissues and cell lines, and to examine the effect of ghrelin on GOAT expression in cultured prostate cancer cell lines." (PMID 23879975, 2013). "We propose that the RWPE-1 prostate cell line and the PC3 prostate cancer cell line may be useful model cell lines to investigate GOAT/MBOAT4 regulation and function." (PMID 23879975, 2013).
colitis (4 papers, 2021 to 2024). Inflammation of the colon. "Additionally, Mboat4 encodes ghrelin-O-acyltransferase (GOAT), which has been reported to be overexpressed in colitis." (PMID 39600697, 2024). "Furthermore, the upregulation of MBOAT4 can have negative implications for the gut health, as indirectly suggested by the attenuation of colitis associated with reduced inflammation and improved intestinal tight junction function, when this gene is knockdown in mice." (PMID 33731211, 2021).
Hypoglycemia (4 papers, 2012 to 2024). A decreased concentration of glucose in the blood. "Mboat4−/− (the gene for GOAT) knockout mice do not show any phenotypic differences in response to a standard or high-fat diet, but long-term caloric restriction leads to increased weight loss and hypoglycemia due to GH insufficiency." (PMID 38019584, 2024).
pituitary adenomas (1 paper, 2015). "In addition, MBOAT4 expression levels were slightly downregulated in NFPAs and, similar to that found in all the pituitary adenomas included in this study, we found that In1-ghrelin was significantly overexpressed in NFPAs." (PMID 25737012, 2015). "Moreover, the presence of MBOAT4 and In1-ghrelin has not yet been determined in pituitary adenomas." (PMID 25737012, 2015).
pituitary tumor (1 paper, 2015). A benign or malignant neoplasm affecting the pituitary gland. "Therefore, the aim of this study was to systematically analyze, for the first time, the side-by-side presence of different components of the ghrelin system: native ghrelin, In1-ghrelin variant, MBOAT4 enzyme, GHSR1a and GHSR1b, in normal pituitaries and in all major types of human pituitary tumors." (PMID 25737012, 2015).
MBOAT4 also shares sentences with these, for which no sentence is quoted: Obesity (24 papers); tumor (6); cancer (5); type 2 diabetes (4); diabetes (3); Anorexia (2); breast carcinoma (2); gastrointestinal disorders (2); Insulin resistance (2); alcohol abuse (1); Alzheimer disease (1); anorexia nervosa (1); cognitive deficits (1); dementia (1); epilepsy (1); Gastroenteropancreatic Neuroendocrine Tumors (1); Glucose intolerance (1); Hyperglycemia (1); Impaired glucose tolerance (1); insulinoma (1); lung carcinoma (1); metabolic disorders (1); migraine (1); neuroendocrine tumor (1); sarcopenia (1); Sepsis (1).